LRRN3 (leucine rich repeat neuronal 3)
Synonyms: NLRR-3; NLRR3; FLJ11129; FIGLER5
Tractability: Small molecule: it belongs to a druggable protein family. Antibody: UniProt predicts a signal peptide or a membrane-spanning region; its Gene Ontology location is reachable by antibodies, with medium confidence.
Gene: Protein-coding gene on chromosome 7 (111,091,006 to 111,125,454, forward strand). Ensembl gene ENSG00000173114.
Subcellular location: Membrane
Subcellular location (Human Protein Atlas): Cytosol; Nucleoplasm
Gene Ontology:
Molecular function: protein binding; signaling receptor activity
Cellular component: plasma membrane; membrane
Genetic constraint (gnomAD): Loss-of-function variants: 15 observed, 41.28 expected, observed/expected ratio (o/e) 0.36, 90% interval 0.24 to 0.56. The upper end of that interval is the gene's LOEUF score, 0.56, which puts it in group 2 of 6, group 1 being the genes least tolerant of losing a copy. Missense variants: 746 observed, 879.93 expected, observed/expected ratio (o/e) 0.85, 90% interval 0.8 to 0.9. Synonymous variants: 308 observed, 314.04 expected, observed/expected ratio (o/e) 0.98, 90% interval 0.89 to 1.08.
Homologues: Orthologues: chimpanzee LRRN3 (100% identical), rabbit LRRN3 (95% identical), dog LRRN3 (95% identical), pig LRRN3 (94% identical), guinea pig LRRN3 (93% identical), mouse Lrrn3 (88% identical), rat Lrrn3 (87% identical), tropical clawed frog lrrn3 (70% identical), zebrafish lrrn3b (59% identical), zebrafish lrrn3a (53% identical). Paralogues in human: LRRN1 (54% identical), LRRN2 (46% identical), SLIT2 (21% identical), SLIT1 (21% identical), LINGO2 (20% identical), LINGO1 (20% identical), SLIT3 (19% identical), LRRC70 (19% identical), LRFN5 (18% identical), LRFN3 (18% identical), LRFN2 (18% identical), LRFN1 (18% identical), and 13 more.
Diseases named in the same sentence as LRRN3 in open-access papers:
LRRN3 is named in the same sentence as 27 diseases in open-access papers, as found by Europe PMC text mining. Sharing a sentence is not in itself a finding about the gene and the disease. The quoted sentences say what the papers report.
autism (4 papers, 2010 to 2019). Persistent deficits in social interaction and communication and interaction as well as a markedly restricted repertoire of activity and interest as well as repetitive patterns of behavior. "Functionally, LRRN3 has been implicated in autism, antidepressant action, and cortical thickness (alterations of which are associated with conduct and psychopathic features)." (PMID 30569215, 2019). "The region at 50–52 Mb on CFA14, associated with Stranger-directed interest, includes LRRN3, a strong risk gene for autism in humans." (PMID 31611599, 2019).
breast carcinoma (2 papers, 2025). "For example, peripheral T cells in breast cancer exhibit transient downregulation of CD28/CD27/leucine rich repeat neuronal protein 3 (LRRN3) expression postchemotherapy, while TGF‐β induced by chemoradiotherapy promotes senescent CD27−CD8+ T cells in cervical cancer." (PMID 41427020, 2025). "Among other family members, LRRN3, LRRN4, and LRRN4CL were uniformly downregulated in breast cancer tissues." (PMID 41458604, 2025). "Notably, our analysis revealed significant downregulation of LRRN1, LRRN3, and LRRN4CL in breast cancer tissues." (PMID 41458604, 2025). "The observed differential expression patterns, particularly the consistent downregulation of LRRN1, LRRN3, and LRRN4CL coupled with LRRN2 upregulation, prompted us to focus our subsequent investigations on elucidating the specific mechanisms of these proteins in breast cancer metastasis." (PMID 41458604, 2025).
colorectal cancer (2 papers, 2022 to 2025). A primary or metastatic malignant neoplasm that affects the colon or rectum. "LRRN4 has been shown to promote colorectal cancer malignancy through activation of the RAS/MAPK pathway, while LRRN3 has been associated with a lower risk of mesothelioma." (PMID 41458604, 2025). "Our method is able to identify the known cancer drivers and further nominate candidates that exhibit higher breakpoint proximity than expected by random chance, such as DMD and LRRN3 in esophageal cancer, NF1 in ovarian cancer, CDK12 in uterine cancer, and WWOX in colorectal cancer." (PMID 36163358, 2022).
Parkinson disease (2 papers, 2023 to 2024). A progressive degenerative disorder of the central nervous system characterized by loss of dopamine producing neurons in the substantia nigra and the presence of Lewy bodies in the substantia nigra and locus coeruleus. "The findings suggest that LRRN3 can be considered a potential biomarker only in the early stages of Parkinson’s disease." (PMID 39061965, 2024).
autism spectrum disorder (1 paper, 2025). A spectrum of developmental disorders that includes autism, and Asperger syndrome. "LRRN3 is involved in neural development and maintenance and its polymorphisms may be associated with autism spectrum disorder." (PMID 40259945, 2025).
esophageal cancer (1 paper, 2022). A primary or metastatic malignant neoplasm involving the esophagus. "We also identified LRRN3 as a driver candidate in esophageal cancer with SVs in 20.7% of the samples." (PMID 36163358, 2022).
gastric cancer (1 paper, 2022). A primary or metastatic malignant neoplasm involving the stomach. "The amplificated CNV of immune‐related genes in gastric cancer tissues was accompanied by the increase of their mRNA level (e.g., LRRN3 and NFATC2), and vice versa (e.g., MAGEC1)." (PMID 34582114, 2022).
HIV-1 infection (1 paper, 2013). The type species of lentivirus and the etiologic agent of acquired immunodeficiency syndrome (AIDS). "Our results suggest that ADA, LRRN3 and telomerase activity in CD8+ T cells may serve as novel, clinically relevant biomarkers of immune status in HIV-1 infection, specifically by demonstrating the degree to which CD8+ T cells have progressed to the end stage of replicative senescence." (PMID 23717651, 2013).
lung adenocarcinoma (1 paper, 2020). A carcinoma that arises from the lung and is characterized by the presence of malignant glandular epithelial cells. "Furthermore, the expression levels of ANXA1, VEGFC, PDGFC and LRRN3 were significantly positively associated with the survival of lung adenocarcinoma." (PMID 33293474, 2020).
melanoma (1 paper, 2020). A malignant, usually aggressive tumor composed of atypical, neoplastic melanocytes. "However, the genes ANXA1, PDGFC, VEGFC and LRRN3 were downregulated in CL1-0 shMITF-harboring cells, while they were upregulated in si-MITF melanoma 501MEL cells." (PMID 33293474, 2020).
sarcoidosis (1 paper, 2022). Sarcoidosis is a multisystemic disorder of unknown cause characterized by the formation of immune granulomas in involved organs. "In addition, we found that LRRN3, IFI44, LHFPL2, RTP4, and EPHX2 were all involved in diagnosing sarcoidosis, which might shed light on the mechanisms of sarcoidosis and provide potential biomarkers for diagnosis." (PMID 36405616, 2022).
cancer (4 papers, 2013 to 2023). A tumor composed of atypical neoplastic, often pleomorphic cells that invade other tissues. "Application to multi-block graphical LASSO on real (epigenetic and transcriptomic) data from the Norwegian Women and Cancer study reveals a central/credible and novel cross-OMIC role of LRRN3 in the biological response to smoking." (PMID 38143734, 2023).
heart disease (1 paper, 2016). "LRRN3 appears to be involved mainly in neurodevelopment and its possible role to heart disease is currently unclear." (PMID 26837704, 2016).
neurodegenerative disease (1 paper, 2024). A disorder of the central nervous system characterized by gradual and progressive loss of neural tissue and neurologic function. "Apparently, LRRN3 may be involved in the development of neurodegenerative processes in PD, while the MEF2C and SLC22A4 genes might be involved in the development of general compensatory processes typical for various neurodegenerative diseases." (PMID 39061965, 2024).
LRRN3 also shares sentences with these, for which no sentence is quoted: mesothelioma (2 papers); neuroblastoma (2); Anxiety (1); depression (1); endothelial dysfunction (1); ischemic stroke (1); ovarian carcinoma (1); pancreatic cancer (1); prostate carcinoma (1); schizophrenia (1); Stroke (1); tumor (1); uterine cancer (1).